FFAR1 (free fatty acid receptor 1)
Diseases named in the same sentence as FFAR1 in open-access papers (continued):
Sharing a sentence is not in itself a finding about the gene and the disease.
colitis (5 papers, 2021 to 2025). Inflammation of the colon. "Moreover, we observed that during DSS-induced colitis, expression of FFAR1 was significantly increased, while FFAR2 decreased in the colon." (PMID 34444876, 2021). "These two FAs decreased the inflammatory response in macrophages mediated via FFAR1, FFAR2, FFAR3, and AMPK; attenuated the development of colitis; and were involved in the elimination of C. glabrata from the gut." (PMID 36144406, 2022). "However, the role of FFAR1 signaling in colitis remains unclear given the lack of effect elicited by the agonist of this receptor." (PMID 34444876, 2021). "Furthermore, we observed a robust increase in FFAR1 expression, with no apparent change in FFAR2–4 during TNBS-induced colitis." (PMID 34444876, 2021).
prostate carcinoma (5 papers, 2020 to 2023). A carcinoma that arises from epithelial cells of the prostate gland. "FFAR1 activation promotes lung cancer and melanoma and prostate cancer, while FFAR4 activation inhibits these processes." (PMID 35785152, 2022). "DHA significantly induced growth inhibition and apoptosis of human androgen-dependent prostate cancer cells via inactivating YAP by promoting phosphorylation and cytoplasmic translocation pathways (FFAR1/FFAR4-Gas-PKA-Hippo)." (PMID 36117589, 2022).
depression (4 papers, 2019 to 2021). "This discovery highlights the possibility that developing small molecules aimed at inhibiting the association between PDE4A5 and FFAR1 could provide novel therapeutics for treating patient’s depression caused by their diet." (PMID 31076569, 2019). "Moreover, our group recently demonstrated that repeated intracerebroventricular administration of GW9508 reduced the duration of immobility behavior in the forced swim test, suggesting that activation of brain FFAR1 may downregulate depression-related behavior." (PMID 34489696, 2021). "Regulation of the expression of different FFA receptors at the mRNA level, especially FFAR1, in the hypothalamus in response to DIO and GIO represent a potential mechanism to regulate depression." (PMID 31076569, 2019).
injury (4 papers, 2015 to 2025). Damage inflicted on the body as the direct or indirect result of an external force, with or without disruption of structural continuity. "Another study could further show that PBI-4050 reduced renal damage in wild-type but not FFAR1 knock-out mice suffering from adenine-induced kidney injury, suggesting that therapeutic efficacy of this compound relies on the activation of FFAR1 rather than inhibition of GPR84 in this model." (PMID 33578942, 2021).
melanoma (4 papers, 2016 to 2022). A malignant, usually aggressive tumor composed of atypical, neoplastic melanocytes. "Furthermore, TAK875 and GW9508 acting through FFAR1, elicited potent anti-proliferative effects in multiple types of human melanoma cells lines, suggesting that FFAR1 may play a complex role in proliferation that is cell and tissue specific." (PMID 33256729, 2020).
colorectal cancer (3 papers, 2022 to 2025). A primary or metastatic malignant neoplasm that affects the colon or rectum. "For the “tumor” variable in the colorectal cancer dataset GSE199057, the Reactome pathways “acetylcholine regulates insulin secretion” and “fatty acids bound to GPR40 (FFAR1) regulate insulin secretion” were both significantly enriched." (PMID 40050559, 2025).
Hypoinsulinemia (3 papers, 2013 to 2022). A decreased concentration of insulin in the blood. "In addition, FFAR1 overexpression causes hypoinsulinemia and autophagy hyperactivation reduces insulin release in β-cells, suggesting that an additional crosstalk might be occurring between FFAR1 and autophagy, specifically in pancreatic β-cells." (PMID 30972025, 2019).
lung carcinoma (3 papers, 2022 to 2025). "The clinical TCGA data showed a significant down-regulation of FFAR2, but not FFAR1, FFAR3, and FFAR4, in lung cancer, and a negative correlation with TLR2 and TLR3." (PMID 37287005, 2023).
neuroblastoma (3 papers, 2020 to 2022). Neuroblastoma (NB) is the most common solid, extracranial childhood tumor. "A previous study shows that activation of FFAR1 induces the phosphorylation of CREB and of extracellular-regulated kinase (ERK) 1/2 in primary hippocampal neurons and in a human neuroblastoma cell line." (PMID 35408893, 2022).
pancreatic cancer (3 papers, 2019 to 2022). "In some tumors, FFAR1 and FFAR4 have the opposite effect; for example, FFAR1 activation inhibits the motile activity of pancreatic cancer and osteosarcoma cells, while FFAR4 activation promotes these activities." (PMID 35785152, 2022).
asthma (2 papers, 2020 to 2023). "Arguably, FFAR1 activation can serve as a novel therapeutic target to broncho-protect human airways in airway diseases such as asthma and COPD." (PMID 33256729, 2020). "The FFAR1 agonist TAK875 attenuated MLC phosphorylation in β2AR-desensitized HASM cells, indicating the potential of this compound to curb AHR in severe asthma." (PMID 33256729, 2020).
fibrosis (2 papers, 2022 to 2023). the formation of excess fibrous connective tissue in an organ or tissue in a reparative or reactive process. "In addition, it is possible that the hepatoprotective effect of QS-528 on this hepatotoxicity model is also associated with the ability of FFAR1 agonists to prevent the development of CCl4-induced fibrosis via the regulation of macrophages, fibroblasts/myofibroblasts and epithelial cells." (PMID 36615590, 2023).
ischemic stroke (2 papers, 2022 to 2023). A stroke disorder caused by obstruction of blood flow to the brain, due to thrombotic (local blood clot formation) or embolic (due to a blood clot or other material traveling from another site) event. "Firstly, we demonstrated that FFAR1 was a hub gene in ischemic stroke by STEM cluster analysis, KEGG-GO enrichment analysis, and PPI analysis from GSE128623." (PMID 36117589, 2022). "However, how candesartan regulates FFAR1/ITGA4 axis in the treatment of ischemic stroke needs further investigations." (PMID 36117589, 2022).
ovarian carcinoma (2 papers, 2020 to 2022). A malignant neoplasm originating from the surface ovarian epithelium. "Pharmacological experiments in cells in culture showing that FFAR1 activation promotes ovarian cancer cell proliferation support the contribution of this receptor to tumor growth." (PMID 33113952, 2020). "Survival analyses of FFAR1 and FFAR4 in ovarian cancer (Kaplan–Meier plotter)." (PMID 35785152, 2022).
acne (1 paper, 2016). An inflammatory process of the sebaceous glands which is characterized by comedones, nodules, papules and/or pustules on the skin. "The expression of Ffar1 and Ffar2 in acne lesions is not yet quantified." (PMID 27834859, 2016).
alcoholic hepatitis (1 paper, 2021). Acute hepatitis resulting from ingestion of alcohol. "More recently, omega-3 fatty acids, which are known agonists of FFAR1 and FFAR4, have shown efficacy in treating NAFLD, NASH, alcoholic hepatitis, and IFALD." (PMID 33897464, 2021).
Autoimmunity (1 paper, 2024). The occurrence of an immune reaction against the organism's own cells or tissues. "Future studies should aim to validate these findings across different models and further investigate the functional roles of Ffar1 and Scg2 in human CNS inflammation and autoimmunity." (PMID 39518908, 2024).
cocaine abuse (1 paper, 2021). Disorders related or resulting from use of cocaine. "Although future studies are necessary to elucidate the precise roles of FFAR1 in cocaine action including the locomotor responses, this study would promote a better understanding of the neurophysiological function of FFAR1 as a potential therapeutic target of cocaine abuse." (PMID 34489696, 2021).
eating disorder (1 paper, 2023). A broad group of psychological disorders with abnormal eating behaviors leading to physiological effects from overeating or insufficient food intake. "Finally, numerous studies concluded that FFAR1 and FFAR4, could plays a critical role in various physiologic homeostasis mechanisms especially the regulation of appetite, eating disorder, or food preference." (PMID 36941594, 2023).
esophageal cancer (1 paper, 2022). A primary or metastatic malignant neoplasm involving the esophagus. "FFAR1 activation inhibits the migration and invasion in fibrosarcoma cells, whereas FFAR4 activation stimulates the migration and invasion of esophageal cancer cells." (PMID 35785152, 2022).
liver disease (1 paper, 2021). "However, omega-3 FAs are among the most potent FFAR1 agonists, are highly concentrated in fish, seafood, nuts, and plant oils, and have been used successfully in treating liver disease." (PMID 33897464, 2021). "Experimental models of these liver diseases used in conjunction with FFAR1 knockout animals and/or FFAR1 antagonists offer the potential to further elucidate the disease mechanisms and better characterize FFAR1 as a target for therapeutic intervention with omega-3 FAs or FFAR1-specific agonists." (PMID 33897464, 2021). "Furthermore, the expression of FFAR1 on hepatocytes and FFAR4 on hepatic Kupffer cells makes targeting these receptors as an intuitive strategy for treating liver disease." (PMID 33897464, 2021). "FFAR1-specific agonists have not been studied in liver disease." (PMID 33897464, 2021).
cancer (12 papers, 2016 to 2024). A tumor composed of atypical neoplastic, often pleomorphic cells that invade other tissues. "Notably, the free fatty acid receptors FFAR1 (GPR40), FFAR2 (GPR43), FFAR3 (GPR41), and FFAR4 (GPR120) have the potential to bridge the genetic and environmental factors associated with cancer." (PMID 38243188, 2024).
metabolic disease (8 papers, 2016 to 2024). A congenital disorder (due to inherited enzyme abnormality) or acquired (due to failure of a metabolically important organ) disorder resulting from an abnormal metabolic process. "Both FFAR1 and FFAR2 have been suggested to act as receptors for long-chain fatty acids and play important roles in various physiological and pathological processes, including metabolic disorders." (PMID 34445796, 2021).
tumor (7 papers, 2018 to 2025). "It has been proven that CHIR-99021 and FFAR1 modulator one are beneficial for tumor treatments." (PMID 35812755, 2022). "Several reports have recently shown that FFAR1 is expressed in various tumors and that it may influence tumor growth and progression." (PMID 29330456, 2018). "The goal of this study was to examine the novel role of the free fatty-acid receptor-1 (FFA1/GPR40), a cell-surface expressed G protein-coupled receptor that is activated by medium-to-long chained dietary fats, in modulation of pRCC cell migration invasion, proliferation and tumor growth." (PMID 37355607, 2023).
infectious disease (1 paper, 2015). A disorder directly resulting from the presence and activity of a microbial, viral, or parasitic agent in humans. "Long chain fatty acids (LCFAs), which are ligands for the G-protein coupled receptor FFAR1 (GPR40), are increased in cow plasma after parturition, a period in which they are highly susceptible to infectious diseases." (PMID 25790461, 2015).
retinopathies (1 paper, 2022). "Modulating FFAR1 may be clinically advantageous in controlling NV-AMD and other retinopathies." (PMID 35167498, 2022).
FFAR1 also shares sentences with these, for which no sentence is quoted: Alzheimer disease (6 papers); Glucose intolerance (6); cognitive deficits (5); hyperlipidemia (5); steatosis (4); colon cancer (3); infection (3); neurodegenerative disease (3); neuropathic pain (3); periodontitis (3); pulmonary fibrosis (3); Stroke (3); airway hyperresponsiveness (2); bacterial infection (2); glucose metabolism disorders (2); hypertriglyceridemia (2); inflammation (2); mood disorder (2); nonalcoholic steatohepatitis (2); osteoporosis (2); renal carcinoma (2); ulcerative colitis (2); Ureteral obstruction (2); age (1); allergic contact dermatitis (1); autoimmune disease (1); benign prostatic hyperplasia (1); beta cell tumor (1); bone cancer (1); cardiovascular diseases (1).
A further 27 diseases each share a sentence with FFAR1 in 1 paper.